ALB (albumin)
Diseases named in the same sentence as ALB in open-access papers (continued):
Sharing a sentence is not in itself a finding about the gene and the disease.
depression (continued). "In terms of the overall biological changes corresponding to depression, the changes in albumin are relatively larger, which have important implications related to the relationship between biological factors and mental states." (PMID 35959294, 2022). "BD patients experiencing manic episodes and depressive episodes both showed decreased albumin levels compared with HCs, and the decline in former was more obvious." (PMID 35216557, 2022). "Nevertheless, our result still make sense because it corroborate serum albumin as a potential early warning biomarker of depression in CLD patients." (PMID 34983435, 2022). "Based on the network topology combined with the PPI analysis, we obtained that TCEF can regulate depression through five core targets, namely, ALB, AKT1, TNF, ESR1, and CTNNB1." (PMID 36506595, 2022). "Further prospective cohort studies are warranted to confirm the role of serum albumin in depression among CLD patients." (PMID 34983435, 2022). "Correlation between body mass index, upper arm circumference, calf circumference, and albumin and depression." (PMID 35959294, 2022). "Some studies found that serum albumin levels were lower in people with depression and that there was a link between serum albumin and total serum/plasma TRP." (PMID 36339964, 2022). "In this study, a low serum albumin level was noted to be a predictive factor for depression among participants." (PMID 36612797, 2022). "In particular, the overall burden of comorbidities, preexisting diagnosis of depression, and a low albumin level at baseline are significant and independently associated with infection." (PMID 34160237, 2021). "In the present study, many anti-depressant targets of EMO against depression were associated with the inflammatory response such as IL6, TNF, IL10, CRP, IL1B, CTLA4, ALB and IL2." (PMID 34051074, 2021). "Multivariate models showed that worse quality of life (OR 1.3; p < 0.001) predicted depression while marital status (with a partner; OR 0.3; p = 0.025) and albumin levels (OR 0.1; p = 0.027) were protective factors." (PMID 33805492, 2021). "IBD patients with symptoms of anxiety/depression were older (p = 0.0003), and had lower levels of ALB [35.3 (29.6, 39.7) vs 37.5 (33.1, 42.2), p = 0.0017] compared to those without." (PMID 33446900, 2021). "Based on multivariable modeling, overall comorbidities, depression, and low albumin levels at the time of rectal swab collection were independently associated with subsequent Klebsiella infection (i.e., cases)." (PMID 34160237, 2021). "It is possible that poor nutritional status leads to higher mortality, at least partly via reductions in physical activity levels, and about psychological problems, albumin levels were found to have a major relationship with IL-6 and depression ratings." (PMID 34225818, 2021). "After 4 months of treatment,significant increases in BHB and albumin, and a decrease in depression, were observed in the intervention group." (PMID 33920655, 2021). "Those participants with depression symptoms had significantly lower hemoglobin, albumin, and total protein (P < 0.01), as well as higher direct bilirubin (P < 0.05), high-density lipoprotein (P < 0.05), and aspartate aminotransferase (P < 0.01)." (PMID 34007268, 2021). "Although patients with low muscle mass had lower micronutrient concentrations compared to those patients with normal muscle mass, only serum albumin showed significant correlations with quality of life at admission and depression symptoms at 6 weeks." (PMID 32190345, 2020). "As for the factors related to functional recovery after discharge, previous studies had shown that age, cognition, depression, albumin, and IADL at 2 weeks before admission affected ADL in older patients." (PMID 32131744, 2020). "Some oxidative stress biomarkers such as albumin, HDL cholesterol, and uric acid are likely to be associated with depression." (PMID 32518578, 2020).
depression (continued). "Concerning associations with clinical symptomatology, the only CSF parameters that correlated with symptom scores were IL-8 (depression), respectively albumin and IgG (schizophrenia)." (PMID 30116031, 2019). "Among black men only, high-risk levels of systolic BP (aOR = 1.7, 95% CI: 1.1–2.7) and serum albumin (aOR = 1.7, 95% CI: 1.0–2.9) predicted depression." (PMID 30154326, 2018). "Gait speed, hemoglobin, serum albumin, exhaustion, and depression were significantly worse in patients with all types of cancers than in pair-matched controls." (PMID 29707115, 2018). "The timed get-up and go test (TGUG), serum albumin, hemoglobin, presence of exhaustion, and depression were significantly worse in patients with all types of cancers than in controls." (PMID 29707115, 2018). "Previous studies have revealed a correlation between serum albumin levels with symptoms of depression in patients on MHD." (PMID 28455662, 2017). "For example, depression reflects the psychological domain, and the albumin levels or the nutritional status anchor many items in measuring quality of life." (PMID 28931925, 2017). "For the subgroup of samples with depression, all combinations of the biomarkers total protein, albumin, ApoE4 status, cGMP, cAMP, age and thyroid problems were tested for their predictive performance (AD vs control)." (PMID 28274265, 2017). "In ESRD patients, FACIT-F scale scores have been shown to correlate significantly with the presence of cardiovascular diseases, depression, poorer exercise tolerance, and serum albumin levels." (PMID 26998414, 2016). "All patients were assessed before and after four weeks of training through clinical assessment, measurement of fibrinogen and albumin levels, spirometry, 6-minute Walk Test (6MWT), quality of life survey, and anxiety and depression scale." (PMID 25065540, 2014). "With respect to inflammation, only the somatic symptom dimension of depression was consistently associated with elevated levels of IL-18, IL-1-Ra, fibrinogen, CRP and decreased albumin levels." (PMID 23967272, 2013). "In this study we found that there were no statistical significance differences as regard baseline scores of anxiety, depression and aggression among normal albumin values using Fisher Exact & P value (>0.05) and also along seven weeks of follow up among cases." (PMID 23738225, 2013). "We found that the severity levels of pain, depression, appetite, nausea, drowsiness, well-being, and shortness of breath and albumin level were predictive of the severity of fatigue at the time of the initial consultation." (PMID 22985058, 2012). "Both participants had a previous history of depression, ongoing antidepressive treatment, increased CSF/serum albumin ratio (14.5 and 12.0) and a medical history of atrial fibrillation." (PMID 23049916, 2012). "Measurements included anthropometry; body composition indicators; CD4 count, haemoglobin and albumin; as well as incidence rates of opportunistic infections; depression and quality of life scores." (PMID 22192583, 2011). "The levels of fasting blood glucose (FBG), HBA1c, and urinary albumin were higher in those with depression." (PMID 20535315, 2010). "This suggests that albumin may act as a protective factor by reducing inflammation and oxidative stress, which are often elevated in individuals with depression." (PMID 40718002, 2025). "These included age, marital status, occupation, body mass index (BMI), poor lifestyle habits, tumor stage, therapy method, combined chronic diseases, personal monthly income, sleep quality, social support, depression, stress, white blood cell count, and albumin levels." (PMID 41584588, 2025). "The 25 (OH)D level was positively correlated with age, albumin, Hb, ALT, T-bil, calcium, PCS, MCS, and CCI, and negatively correlated with TG, insulin, HOMA_IR, PLT, eGFR, phosphorus, iPTH, the HBM score and depression scores in the univariate association analysis." (PMID 40618164, 2025).
depression (continued). "Moreover, a meta-analysis revealed that factors such as age, education, comorbidities, BMI, albumin levels, nutritional status, symptom clusters, depression, and daily living abilities significantly influence frailty in oncology patients." (PMID 40706088, 2025). "The most consistent finding is a link between low albumin and more severe depression." (PMID 41463102, 2025). "However, recent studies have highlighted the potential roles of serum albumin and monocyte counts in both healthy individuals and those with depression." (PMID 40718002, 2025). "A decrease in albumin may result in the dysregulation of oxidative stress, with increased levels of free radicals and oxidative injury being observable in patients with depression." (PMID 39950171, 2025). "Thus, the MR analysis was harnessed to scrutinize the causal interplay between depression and testosterone, BMI, triglycerides, HDL, ALP, GGT, TB, albumin, BUN, WBC count, MCV, and RDW." (PMID 40714919, 2025). "Given the critical roles in diseases, physiological functions, and inflammation assessment, the combined evaluation of albumin concentration and RDW may provide valuable information for assessing the risk of depression." (PMID 39950171, 2025). "Following covariate screening, sixteen variables (age, gender, race, BMI, triglycerides, HDL, ALP, GGT, TB, albumin, BUN, bicarbonate, WBC count, RBC count, MCV, and RDW) were discerned and consolidated into a risk prediction model (model 1) for depression via multivariate logistic regression." (PMID 40714919, 2025). "The association of globulin and albumin-globulin ratio (AGR) with depression in cancer and non-cancer populations remains understudied." (PMID 40276074, 2025). "The mechanism might be that depression might involve inflammatory, immune, oxidative, and nitrosative stress with microprogrammed expression responses, and albumin played an essential role in this process." (PMID 39717378, 2024). "Lower AGR levels may reflect such interaction imbalances, such as lower albumin levels being related to immune and hormonal imbalances in the body, exacerbating depression symptoms." (PMID 39421614, 2024). "After antidepressant treatment, albumin levels gradually increase in depression patients." (PMID 39421614, 2024). "The results imply that low albumin and elevated globulin have a connection with depression." (PMID 39421614, 2024). "Additionally, studies have found that depression patients have lower total serum protein and albumin levels, while globulin levels are higher, possibly reflecting abnormal protein metabolism in these patients." (PMID 39421614, 2024). "Albumin also carries and transports important metabolites such as fatty acids, magnesium ions, and thyroid hormones, indirectly influencing the occurrence of depression." (PMID 39421614, 2024). "Furthermore, lower albumin levels can reduce the utilization of tryptophan, a key amino acid, affecting serotonin production, which is crucial for the pathophysiology of depression." (PMID 39421614, 2024). "Lower albumin levels may lead to oxidative stress imbalance, particularly evident in depression patients who usually exhibit higher levels of free radicals and oxidative damage." (PMID 39421614, 2024). "This independent connection might indicate that serum albumin is a valuable screening biomarker for depression." (PMID 37880606, 2023). "The function of serum albumin as a protein with free-radical scavenging characteristics may help to explain, at least in part, the role that albumin has in the development of depression." (PMID 37880606, 2023). "However, there has been little investigation into the relationship between depression and serum albumin levels in community-dwelling persons." (PMID 37880606, 2023). "Albumin could therefore be a novel indicator for evaluating the progress and severity of depression." (PMID 37340352, 2023).
depression (continued). "Albumin levels could affect the development of depression since serum albumin levels are significantly lower in patients with depressive disorder than in healthy individuals and are correlated with disease severity." (PMID 37340352, 2023). "We used a nationwide community-based household sample of > 17-year-old male and female adults to investigate whether there is an association between the presence of depression, as defined by the PHQ-9 scale, and the serum level of albumin." (PMID 37880606, 2023). "The specific hypothesis of this research is that lower serum albumin levels significantly increase the severity and probability of developing depression." (PMID 37880606, 2023). "Our research found an inverse relationship between serum albumin and depression." (PMID 37880606, 2023). "This research aimed to examine the relationship between serum albumin and depression in a population-based sample and whether it differs depending on other possible confounders." (PMID 37880606, 2023). "When comparing the patterns with respect to the BD depression/mixed state classification and the BD mania/depression classification, we found that creatine kinase, lowering of mood, albumin, cholesterol, age, hemoglobin, percentage of monocyte contributed most in both models." (PMID 38179244, 2023). "Another author reported lower serum albumin and not urea, calcium, or phosphate to be significantly associated with depression." (PMID 37692732, 2023). "Finally, the univariate and multivariate linear regression analysis models showed that depression severity which was expressed by the continuous variable (score of PHQ-9) was inversely related to serum albumin level." (PMID 37880606, 2023). "This research demonstrates a substantial inverse relationship between depression and serum albumin." (PMID 37880606, 2023). "Our findings for the association between albumin and depressive symptoms were similar to previous reports, but those were mostly related to comorbid physical diseases and hence did not represent the direct association between albumin and depression." (PMID 37340352, 2023). "As for nutritional status, low albumin was with depression among T2DM patients." (PMID 35457752, 2022). "Our subgroup analysis showed that the association between serum albumin and depression was not significant among patients with CAP ≥274 dB/m." (PMID 34983435, 2022). "Additionally, several studies demonstrated that there were lower TP and albumin levels in subjects with depression than those in HCs, and decreased TP and albumin levels were related to depressive severity." (PMID 35958662, 2022). "Serum albumin is a routinely tested factor from peripheral blood and can be considered as an easily available biomarker for accurate classification of the severity of the depressive disorder." (PMID 35395781, 2022). "Moreover, we also found that patients with symptoms of anxiety/depression were older, and had lower levels of ALB, which disaccorded to Navabi’s study on USA IBD patients." (PMID 33446900, 2021). "Moreover, several studies have found a connection between psychosocial variables, such as depression and hemodialysis patients’ nutritional status, specifically serum albumin concentration." (PMID 34225818, 2021). "The model built by purposeful selection selected the following variables for inclusion: Elixhauser score, depression, diuretic use, vitamin D use, use of pressors/inotropes, low serum albumin levels (<2.5 g/dl), and exposure to antibiotics with a high risk of microbiome disruption." (PMID 34160234, 2021). "However, there was no longer an association between discontinuation and deprivation, CCI, cancer registration, depression, or having a urinary albumin/creatinine ratio test." (PMID 33882106, 2021).
depression (continued). "We compared physical capabilities (handgrip weakness and slowed walking speed), blood biochemical tests (serum albumin, renal function, and hemoglobin), and self-reported exhaustion and depression between community-dwelling healthy individuals and cancer patients." (PMID 29707115, 2018). "Severity levels of pain, depression, appetite, nausea, drowsiness, well-being, and shortness of breath and the albumin level were predictive of the severity of fatigue at the time of the initial consultation, with pain and low appetite being the most significant predictors." (PMID 22985058, 2012). "Depression has been thought to influence the nutritional status as indicated by albumin levels." (PMID 20703410, 2006). "Furthermore, in a study with a similar index to NPAR, the neutrophil–albumin ratio (NAR), there was a significant association between higher NAR levels and more severe depression in patients with irritable bowel syndrome, which was inconsistent with our findings." (PMID 40182647, 2025). "However, patients with recurrent UC presented a longer disease course, higher baseline levels of CRP and calprotectin, more pronounced anxiety and depression, greater severity of fecal incontinence, and lower BMI, Hb, ALB, and IBD-Q scores than did those with newly diagnosed UC (all P < 0.05)." (PMID 39009899, 2024). "Previous literature suggests a negative association between albumin levels and depression." (PMID 39421614, 2024). "Therefore, the early identification of these risk factors, as well as the management of comorbidities, including depression, and of low blood albumin concentrations, could help to prevent low serum zinc concentrations." (PMID 36678192, 2023). "This cross-sectional study tested the hypothesis that albumin affects depression." (PMID 37340352, 2023). "Finally, the cross-sectional methodology of this study and the use of a self-administered scale to assess depression is its sole potential limitations since it may give a “snapshot” of depression prevalence and albumin serum levels at a single moment in time." (PMID 37880606, 2023). "Our study showed that after adjusting for age and sex, patients with MDD and BD both had decreased albumin levels compared with HCs, and the differences in albumin levels among patients with MDD, BD mania and BD depression were significant." (PMID 35216557, 2022). "Moreover, the decline in serum albumin levels was detected in the rat model of depression." (PMID 35958662, 2022). "Hence, the present study was conducted to delineate the effects of serum levels of β-arrestin-1, FBXW7, CD17, serotonin, albumin, calcium, magnesium, zinc, and copper on severity of depression and anxiety above and beyond the effects of IR and atherogenicity in T2DM." (PMID 35055338, 2022). "Notably, a novel joint index based on the CD4+/CD8+ T cell ratio, albumin concentration, and M% was developed in the present study, and it showed superior sensitivity and specificity to discriminate the severity of the depressive disorder in comparison to the individual significant factors." (PMID 35395781, 2022). "In addition, low protein intake or decreased protein absorption and synthesis, both of which may reduce serum total protein and albumin, and this change may indirectly lead to anxiety, depression, and other mental diseases." (PMID 34007268, 2021). "Furthermore, patients on MHD with symptoms of depression may have lower serum C-peptide, lower serum albumin levels, and lower ABI levels." (PMID 28455662, 2017). "The neutrophil-to-albumin ratio (NPAR) reflects inflammation and nutritional status, while depression significantly impacts survival in chronic disease patients." (PMID 40115342, 2025). "ROC analyses revealed that, in subjects with depression, AUC for RAR was 0.593, which exceeded AUC for RDW (ACU=0.559) and albumin (AUC=0.575)." (PMID 39950171, 2025).